ITGA5 (integrin subunit alpha 5)
Diseases named in the same sentence as ITGA5 in open-access papers (continued):
Sharing a sentence is not in itself a finding about the gene and the disease.
tumor (continued). "In the current study, we hypothesized that cCAFs might retain the expression of ITGA5 after their shedding from the primary tumor and therefore might serve as a novel biomarker to identify cCAFs." (PMID 36831470, 2023). "Downregulation of ITGA5 in tumor cells significantly decreased p‐AKT and VEGFA levels." (PMID 36999964, 2023). "ITGA5/VEGFA coexpression was observed in a tumor cell subpopulation and the decreased endothelial angiogenesis by downregulating ITGA5 could be reversed by VEGFA." (PMID 36999964, 2023). "Additionally, ITGA5 levels appeared to be higher in Group 3 MB, a MYC-driven subtype associated with the increased frequency of tumor recurrence and leptomeningeal dissemination, when compared to other subtypes." (PMID 37430373, 2023). "Interestingly, EC senescence along with ITGA5 surface translocation can be induced by hemodynamic forces, which are known to be profoundly altered in growing tumor vessels." (PMID 36978029, 2023). "There is mounting evidence highlighting a role for ITGA5 in tumor progression, tumor metastasis, and therapy resistance across several malignancies including glioblastoma, colorectal carcinoma, pancreatic cancer, cervical cancer, and non-small cell lung carcinoma." (PMID 37430373, 2023). "However, ITGA5 expression was significantly correlated with tumor size, lymph node metastasis, and TNM pathological stage (P < 0.05)." (PMID 36193075, 2022). "We speculate that elevated ITGA5 expression may be feedback from increased tumor malignancy, involving other mechanisms regulating ITGA5 expression." (PMID 36405728, 2022). "It thus may be anticipated that there was a positive feedback loop between mTORC1 and ITGA5 and ITGA5 specific inhibitors can overcome the defect of rapamycin in anti-tumor therapy of mTORC1-related LSCC." (PMID 36438491, 2022). "Therefore, these six tumor-related genes (ITGA5, PLAU, PLAUR, SERPINE1, TGFB1, and VEGFC) were considered as prognostic biomarkers for HNSCC." (PMID 36425786, 2022). "Administration of ITGA5 siRNA attenuated the tumor growth of LIU-LSC-1 cells in the nude mice." (PMID 36438491, 2022). "ITGA5 has a deep connection with tumor invasion, tumor progression, and chemotherapy resistance." (PMID 35371978, 2022). "However, ITGA5 is highly expressed in a variety of tumors and is involved in tumor progression by promoting cell proliferation and metastasis." (PMID 36193075, 2022). "Elevated ITGA5 promotes LSCC tumor progression through upregulation of ephrin-B2 (EFNB2)." (PMID 36438491, 2022). "In OSCC, ITGA5 facilitated tumor progression and regulated PI3K/AKT pathway." (PMID 33526991, 2021). "ITGA5 was not only expressed by tumor cells but also osteoclasts." (PMID 33420367, 2021). "Besides, the correlation between prognostic gene expression and tumor stem cells was analyzed, and the results showed that ITGA5 and SCL7A1 were significantly negatively correlated with RNAss and DNAss." (PMID 33828988, 2021). "Croset et almiR-30 could inhabit tumor cell invasion by silencing CDH11 or ITGA5 in ER-/PR-negative breast cancer." (PMID 34252359, 2021). "The correlation between prognostic gene expression and tumor stem cell score suggested that ITGA5 and SLC7A1 may have a tumor inhibitory effect, because they were negatively correlated with tumor stemness based on DNAss and RNAss." (PMID 33828988, 2021). "Treating rats with a combination of bevacizumab and cilengitide significantly restricted tumor invasion than with bevacizumab only, suggesting that inhibiting ITGA5 could replenish the antitumor ability of anti-VEGF agents." (PMID 34976814, 2021). "Our result supported the pro-oncogenic effect of ITGA5 and revealed the overexpression of ITGA5 may have a potential and important relationship with tumor-immune infiltration." (PMID 33711961, 2021). "Our study demonstrated that ITGA5 may act as an essential regulator of tumor immune cell infiltration and a valuable prognostic biomarker in gastrointestinal tumors." (PMID 33711961, 2021).
tumor (continued). "This suggested that ITGA5 may play an important role in promoting the recruitment and activation of monocytes, TAMs, Th2 cells and M2 cells in the tumor microenvironment." (PMID 33711961, 2021). "However, the important role of ITGA5 in gastrointestinal tumors and its relationship with tumor immunity are still unclear." (PMID 33711961, 2021). "Combined with our results, we hypothesized that ITGA5 may affect the infiltration of immune cells and tumor purity in SKCM TIME by regulating leukocyte migration." (PMID 34660316, 2021). "In summary, our study demonstrated that ITGA5 may be an essential regulator of tumor immune cell infiltration and a valuable prognostic biomarker in gastrointestinal tumors." (PMID 33711961, 2021). "IHC staining showed that SW1990 + PSCs tumor has a higher positive rate of ITGA5 than SW1990 tumor." (PMID 33613761, 2021). "Of these, ADM, DCBLD2, EREG, ITGA5, MIF, MMP14, and TREM1 were associated with poor prognosis and significantly increased in tumor, while BTG2 was related to favorable prognosis and decreased in tumor." (PMID 35002712, 2021). "Among the tumor specimens with IDH mutation, mRNA levels of SEMA3B, SEMA3C, SEMA3D, SEMA3G, NRP2, PLXNA2, and CDH1 were significantly higher (p < 0.05), while SEMA3F, NRP1, ITGB3, ITGA5, and VEGFA genes were under-expressed (p < 0.05)." (PMID 33036421, 2020). "Furthermore, Itga5-floxed mice demonstrated prolonged survival relative to their WT littermates after tumor removal." (PMID 32082485, 2020). "Indeed, we still observed an increase of neutrophils in Itga5-floxed mice after inoculation with tumor cells, suggesting some redundancy in the pathways that mediate neutrophil recruitment to the premetastatic niche." (PMID 32082485, 2020). "Lower mRNA expression of SEMA3B, SEMA3D, SEMA3G, and PLXNA2 or higher mRNA expression of SEMA3F, NRP1, ITGB3, ITGA5, and VEGFA genes were detected in the older patient group and associated with the higher tumor grade, wild-type status of IDH, and lower rate of survival time (p < 0.05)." (PMID 33036421, 2020). "In addition, we assessed multivariate Cox regressions that included age, sex, tumor stage, lymphatic invasion, tumor location and ITGA5 expression level in the colorectal AC group." (PMID 31600854, 2019). "Blocking ITGA5 drastically attenuates spheroid formation between tumor cells and fibroblasts." (PMID 30710055, 2019). "ITGA5 has an essential role in cell adhesion, migration and tumor invasion." (PMID 31730483, 2019). "Moreover, epidermal growth factor (EGF) derived from activated fibroblasts inside the compact MU microenvironment further sustains ATC ITGA5 expression, which strengthens tumor–stromal interaction inside MUs." (PMID 30710055, 2019). "ITGA5 siRNAs blocked the hMSCs-induced migration and invasion of HCC, while over-expression of ITGA5 promoted the migration and invasion ability in HCC-hMSCs, indicating that the expression of ITGA5 is associated with hMSCs-induced tumor metastasis." (PMID 31142737, 2019). "In addition, Muc1 was downregulated, while Fn1 and Itga5 were upregulated in PDC compared to classical tumours." (PMID 31439856, 2019). "Among them, EGF displayed the highest correlation with ITGA5 in SKOV3 tumor cells." (PMID 30710055, 2019). "To identify the specific cells in the tumor stroma that mainly expressed α5, we performed gene correlation analysis and co‐immunostaining assay between ITGA5 (α5 integrin subunit) and CAF markers, as CAFs have been shown to be abundantly present within the stromal components of carcinomas." (PMID 31600854, 2019). "ITGB1 has been recognized in the processing of metastatic diffusion of tumor cells, and ITGA5 may promote tumor invasion." (PMID 29914539, 2018). "We also identified two different ITGA5 mutations in independent metastases, but not in the primary tumor, of patient 4, suggesting parallel evolution of the two metastatic clones." (PMID 29088767, 2017).
tumor (continued). "ITGA5 exhibits either tumor-promotional or inhibitory properties in different cancers." (PMID 27050274, 2016). "Furthermore, in our in vivo assay, silencing endogenous ITGA5 dramatically promoted tumor cell anoikis upon tail vein injection in nude mice." (PMID 25537511, 2015). "Our results suggest that reduction of ITGA5 levels has similar effects on the HCC cells to miR-26a overexpression, further confirming that ITGA5 may act as a downstream functional mediator of miR-26a during tumor cell anoikis." (PMID 25537511, 2015). "ITGA5 promotes tumor cell adhesion and migration through activating focal adhesion kinase (FAK)." (PMID 25537511, 2015). "E2F5 is cocited with ITGA5 in a paper about miRNA control of tumour cell invasion and metastasis." (PMID 25148247, 2014). "The expression of integrins (e.g., ITGA5) in cancer cells is essential as they allow the cells to attach to the endothelium found within the blood vessels of organs such as the lungs (a secondary site for tumor metastasis)." (PMID 21838876, 2011). "Therefore, detection of cCAFs using ITGA5 as a marker, together with the detection of CTCs, might provide cues to monitor tumor progression and the effects of chemotherapy on metastatic dissemination." (PMID 36831470, 2023). "The increased self-renewal capacity of ITGA5 positive cells despite a lower proliferation rate may be indicative of its functional significance in subpopulation of Group 3 MB cells capable of therapy evasion and driving tumor recurrence." (PMID 37430373, 2023). "Our results suggested that ITGA5 expression was significantly associated with advanced FIGO stage (FIGO 2009, IB2‐IIA2), positive lymph node metastasis, positive lymph vascular space invasion, moderate or poor tumor differentiation, and large tumor size (≥2 cm in diameter)." (PMID 36999964, 2023). "Therefore, ITGA5 is an important gene modifier in oncogenesis and tumor development." (PMID 35371978, 2022). "Furthermore, IHC analysis showed that staining levels of Ki-67 (one of the key indicators of cell growth) and CD31 (an angiogenic marker) were significantly decreased in tumor tissues with deletion of ITGA5, but were more intense in ITGA5-overexpressing tumor tissues." (PMID 36438491, 2022). "Besides, one study shows that ITGA5 is required for the tumor supportive role of fibroblasts." (PMID 35126454, 2021). "ITGA5 may act as an “anchor” for cell positioning, promoting the aggregation, adhesion and migration of partial immune cells and changing components of the tumor microenvironment." (PMID 33711961, 2021). "Besides EGF acting as a soluble factor, the increase in EGF-mediated, increased cell–cell contact might also contribute to tumor cell ITGA5 expression through cell-to-cell contact–dependent factors concerning other integrins." (PMID 30710055, 2019). "Further analysis of the expression relationship between tumor tissues and adjacent paired tissues of ITGA3, ITGA5, and ITGA6 in HNSC reveals that the expressions of ITGA3, ITGA5, and ITGA6 are significantly increased in tumor tissues." (PMID 41602372, 2026). "Analysis indicates that ITGA3, ITGA5, and ITGA6 have activating or inhibiting effects on multiple tumor-related pathways." (PMID 41602372, 2026). "In vitro assays revealed that HUVEC cells exhibited elevated levels of SOX18, ITGA5, and ITGB1 compared to tumor cells and CAFs." (PMID 39823457, 2025). "Our study comprehensively examined the hypoxia pathway in the tumor microenvironment, focusing on the expression of HIF-1α, LOX and ITGA5 and their prognostic implications." (PMID 39857068, 2025). "While matrisome transcripts like ITGA5 and LGALS3 were enriched in TCs and infiltrating stromal cells residing around necrotic regions, the hypoxic tumor regions revealed enhanced expression of IGFBP2 and COL20A1." (PMID 41366031, 2025).
tumor (continued). "Following 21 days of inoculation, the mice were euthanized, and the intact tumor tissues were embedded and sectioned for immune-histochemical staining of Ki67, EMP2, ITGA5, and LC3B." (PMID 39866225, 2025). "In our study, we show that ITGA5, as a downstream target of the PPP2CA, plays multiple critical roles in tumor metabolic reprogramming and metastasis." (PMID 40770810, 2025). "The integrin genes ITGA5 and ITGA7 showed significantly enhanced transcript counts in the GBM tissue compared to the grade III tumor sample." (PMID 41366031, 2025). "ITGA5 and ITGB1 (αV and β1 integrins) mediate cell adhesion and promote survival, proliferation, and migration of tumor cells, thus contributing to tumor progression and metastasis." (PMID 40965626, 2025). "In the hypoxic Pseudo.A region, ITGA5 and SDC4 showed enhanced abundance in subtype 2 TCs in comparison to CLEC5A which was enriched in tumor infiltrating MG/MØs, and LGALS3 that was overall higher in both TCs and surrounding stromal cell types." (PMID 41366031, 2025). "Identifying key signaling pathways and ligand-receptor pairs, such as PSAP-GPR37 and SPP1-(ITGA5+ITGB1), highlights the importance of intercellular communication in modulating tumor behavior." (PMID 39949776, 2025). "The progression of OSF toward malignancy is associated with the upregulation of SPARC, activation of MMP9, and overexpression of ITGA5, promoting ECM degradation, facilitating cell invasion, and driving tumor progression." (PMID 39865173, 2025). "ITGA5, frequently overexpressed in invasive tumors, activates PI3K/AKT signaling to promote tumor proliferation and metastasis, marking it as a crucial driver of malignant transformation in HNSC42,43." (PMID 40021759, 2025). "To explore their functional relevance, we generated ITGA5/ITGB1 double knockdown cell lines and assessed their impact on tumor growth in vivo." (PMID 40770810, 2025). "The therapeutic potential of targeting MMP9, SPARC, and ITGA5 is heightened when considered in combination, as they are involved in different but complementary pathways of ECM remodelling, fibrosis, and tumor progression." (PMID 39865173, 2025). "Antibody staining was detected in both primary and recurrent tumours and was mainly located in the cytoplasmic cell compartment with only WNT9B showing additional nuclear and ITGA5 showing sporadic membranous staining." (PMID 38361045, 2024). "The superior tumor accumulation and penetration of PAZA over PVD were abolished when ITGA5 was knocked out in tumors." (PMID 38482976, 2024). "Specifically, SPP1 released from tumor cells interacted with CD44, ITGAV, ITGA5, ITGB1, and ITGB5 on immune clusters." (PMID 39505867, 2024). "The results from the present study, in particular, show that CD44 expression was increased in the st-FL tumor along with several members of the CD11a/b family (ITGA1, ITGA5, ITGB1, ITGAV), and all integrins were involved in cellular adhesion and migration." (PMID 39456647, 2024). "In this study, the inflammatory response genes (ITGA5, LCK, GCH1, TNFRSF9 and SLC7A1) play different role in immune tumor microenvironment." (PMID 38903179, 2024). "In contrast to the immune response in ACP tumor cells, the NAMPT-ITGB1/ITGA5 signaling network is detected in the immune response of PCP." (PMID 39483146, 2024). "Among stromal fibroblast cells, ITGAV, ITGA1, ITGB1, and ITGB5 were significantly upregulated following IO and, notably, isolated tumor cells found in the stroma showed upregulation of B2M, VIM, ITGA5, ITGB2, and ITGA3." (PMID 39639369, 2024). "Through analysis of the HPA database, we recognized remarkably higher expression levels of specific proteins, including AQP1, ITGA5, MAP3K8, PIK3R3, STC1, and TGM2, in HNSCC tumor tissues." (PMID 38688945, 2024). "Integrin Subunit Alpha 5 (ITGA5), a main member of the integrin alpha chain family, is essential for tumor proliferation, migration, invasion, metastasis, and resistance to chemotherapy." (PMID 36769510, 2023).
tumor (continued). "ITGA5 and VEGFA were coexpressed in clusters 1 and 3, while ANGPT1 and ANGPT2 were minimally expressed in all tumor cells." (PMID 36999964, 2023). "Among the five tumor cell clusters, we found that ITGA5 and VEGFA were coexpressed in tumor clusters (C0‐C4), C0/C2 and C1/C3 were predominant in HPV‐positive and HPV‐negative tumors, respectively." (PMID 36999964, 2023). "ITGA5 is a member of the integrin alpha chain family and combines with ITGB1 to form integrin α5β1, which has been demonstrated to engage in tumor cell adherence." (PMID 38248716, 2023). "We confirmed these results by knocking down ITGA5 or ITGB1, following which the ability of NETs to adhere to tumor cells was greatly reduced." (PMID 37958984, 2023). "To investigate the functional role of the CANX/CALR cycle in ITGA5/B1-mediated adhesion to FN, we used MIA PaCa-2 cells expressing an actin-chromobody tagged with GFP to analyze the spreading of tumor cells on FN-coated plates by live-cell imaging." (PMID 37563605, 2023). "The trials revealed that HK2, ITGA5, and ROCK1 were positively expressed in the tumor (CESC and PANC-1) cell lines compared with the normal (HUCEC) cell lines." (PMID 36837559, 2023). "An increase in TNFAIP2, ICAM1, and ITGA5 expression pointed to a possible TREM1- and HuR-dependent formation of tertiary structures between tumor and myeloid-derived cells within the inflammatory peri-necrotic areas." (PMID 36249290, 2022). "Previous studies have shown that ITGA5 was increased in GBM tissues and promoted tumor cell proliferation and invasiveness, which is consistent with our results." (PMID 36199581, 2022). "Knockout of TSC2 promoted the proliferation, migration, invasion, angiogenesis, and tumor growth abilities of TU177 cells, while these properties were significantly attenuated after depletion of ITGA5." (PMID 36438491, 2022). "As expected, ITGA5, PLAU, PLAUR, SERPINE1, TGFB1, and VEGFC were consistently overexpressed in tumor tissues compared to normal tissues (log2FC > |1| and p ≤ 0.01)." (PMID 36425786, 2022). "The results showed that the ITGA5 and SERPINE1 proteins were mainly expressed in HNSCC tumor cells (with medium staining), while the PLAU protein was enriched in the extracellular matrix of HNSCC (with strong positive reaction)." (PMID 36425786, 2022). "These cells highly expressed the integrin family genes associated with the cell adhesion molecule pathway in contrast to epithelial tumor cells, such as ITGA2, ITGA3, ITGA5, ITGA6, and ITGAV, which were among the top-ranking DEGs." (PMID 36553542, 2022). "The remaining six genes (e.g., PPP3CC, ITGA5, ITK, CDC25B, CCND2, and THY1) were expressed at higher levels in CD45+ TAS as compared to CD45+ tumor." (PMID 36230846, 2022). "IHC staining also showed that tumor sections from nude mice that had been injected subcutaneously with ITGA5 KO2 LIU-LSC-1 cells expressed less EFNB2 protein, while ITGA5 OE TU177 cells showed a higher expression level of EFNB2." (PMID 36438491, 2022). "We matched the expression profiles of three prognostic genes in the TCGA-BLCA and GSE7476 datasets and found that both ITGA5 and ITGA7 were significantly reduced in tumor samples; while ITGB6 was notably overexpressed in the BLCA group (all P< 0.05)." (PMID 36267977, 2022). "The mediation effect of EFNB2 on the ITGA5-related regulation of LSCC growth and metastasis was further verified in vivo using a subcutaneous xenograft tumor model and a tail vein lung cancer metastasis mouse model." (PMID 36438491, 2022). "Of these genes, ITGA5, PLAU, PLAUR, SERPINE1, TGFB1, and VEGFC were significantly highly expressed in tumor compared to normal tissues." (PMID 36425786, 2022).